EXOC3-AS1 (EXOC3 antisense RNA 1)
Synonyms: formerly C5orf55
Gene: Long non-coding RNA gene on chromosome 5 (441,498 to 443,160, reverse strand). Ensembl gene ENSG00000221990.
Subcellular location: Secreted
Diseases named in the same sentence as EXOC3-AS1 in open-access papers:
EXOC3-AS1 is named in the same sentence as 1 disease in open-access papers, as found by Europe PMC text mining. Sharing a sentence is not in itself a finding about the gene and the disease.
EXOC3-AS1 shares sentences with these, for which no sentence is quoted: cervical cancer (1 paper).